TNF (tumor necrosis factor)
Diseases named in the same sentence as TNF in open-access papers (continued):
Sharing a sentence is not in itself a finding about the gene and the disease.
rheumatoid arthritis (continued). "FcγRIIA activation induces the production of pro-inflammatory cytokines, including IFN and TNFα, which are active in the promotion of inflammation, systemic lupus erythematosus (SLE), Kawasaki disease (KD), Grave's disease, and Rheumatoid Arthritis (RA)." (PMID 30941127, 2019). "In a retrospective cohort analysis including a total of 199 rheumatoid arthritis patients, who were newly diagnosed with osteoporosis and receiving bisphosphonate changes in bone mineral density after one year were compared between patients treated with and without TNF inhibitors." (PMID 31795299, 2019). "Blockade of tumor necrosis factor (TNF) was the first cytokine-directed therapy to achieve widespread use and is now used broadly to treat multiple inflammatory diseases including rheumatoid arthritis (RA), psoriasis, and inflammatory bowel disease." (PMID 30340504, 2018). "In this study, the effect of 15-month anti-tumor necrosis factor alpha (TNF-α) treatment on circulating levels of plasma sulfated glycosaminoglycans (GAGs) and the nonsulfated GAG hyaluronic acid (HA) in female rheumatoid arthritis (RA) patients was assessed." (PMID 30227885, 2018). "Although one study showed minimal progression of erosions in patients with rheumatoid arthritis (RA) one year after TNFα inhibition therapy, no studies have investigated very early bone changes after initiation of anti-TNFα treatment." (PMID 28978352, 2017). "Tumor necrosis factor-α (TNF-α) blockers present a revolutionizing therapeutic choice for a number of inflammatory diseases such as Crohn’s disease (CD), ankylosing spondylitis (AS), and rheumatoid arthritis (RA)." (PMID 28337644, 2017). "However, to date, it is not clear whether TNF-α blockade treatment modulated CD154 expression in rheumatoid arthritis." (PMID 28837666, 2017). "The aim of this study was to investigate the effect of intravenous (i.v.)apoptotic cell infusion in ongoing collagen-induced arthritis (CIA) and the interaction of this therapy with other treatments used in rheumatoid arthritis (RA), including methotrexate (MTX) or anti-TNF therapy." (PMID 27516061, 2016). "None of the studies assessed the time-dependent impact of TNF-α inhibitors on the lipid profile of ankylosing spondylitis (AS), psoriatic arthritis (PsA), and rheumatoid arthritis (RA) patients as a group." (PMID 27832797, 2016). "Infliximab is a chimeric, anti-tumor necrosis factor (TNF) monoclonal antibody proven to be effective in patients with active rheumatoid arthritis (RA) not responding to methotrexate (MTX)." (PMID 27038608, 2016). "Furthermore, patients with rheumatoid arthritis receiving anti-TNF-α medication have better periodontal indices and lower levels of TNF-α within the gingival crevicular fluids, which indicates that suppression of proinflammatory cytokines might prove beneficial in suppressing periodontal disease." (PMID 26644840, 2015). "Anti-TNF therapies have been highly efficacious in the management of rheumatoid arthritis (RA), but 25–30% of patients do not show a significant clinical response." (PMID 25848939, 2015). "Interleukin-1β (IL-1β) and tumor necrosis factor-α (TNF-α) play a critical role in the induction and progression of rheumatoid arthritis (RA), and the efficacy of therapies targeting these two inflammatory cytokines confirms their prominent role in the disease." (PMID 26033326, 2015). "Tumor necrosis factor alpha (TNFα) blockers, such as adalimumab (ADA), etanercept (ETA), and infliximab (IFX), are playing a significant role in the treatment of autoimmune inflammatory diseases such as rheumatoid arthritis (RA) and spondyloarthritis (SpA)." (PMID 26064930, 2015). "There are at least five anti-TNF medications (Etanercept, Infliximab, Adalimumab, Golimumab, and Certolizumab) approved by the U.S. Food and Drug Administration (FDA) for the treatment of rheumatoid arthritis (RA)." (PMID 26257732, 2015).
rheumatoid arthritis (continued). "In this study, we investigate how TNF-α inhibition using a targeted monoclonal antibody affects fracture healing in a TNF-α driven animal model of human rheumatoid arthritis (RA) and elucidate the question whether enduring the anti TNF-α therapy after trauma is beneficial or not." (PMID 24885217, 2014). "Also, in rheumatoid arthritis upregulated TTP is found in cells involved in pathogenesis and may be a marker of severe disease, in part because of production stimulated by the TTP target TNF." (PMID 24103357, 2013). "Anti-TNF therapy has been shown to reduce radiographic joint damage in rheumatoid arthritis (RA) independent of clinical response." (PMID 21352592, 2011). "Anti-TNF agents have become standard treatment for patients with rheumatoid arthritis (RA) refractory to non-biologic disease-modifying anti-rheumatic drug (DMARD) therapy." (PMID 20459619, 2010). "Anti-TNF therapies have an established role in rheumatoid arthritis (RA) treatment however in the clinic RA remains a chronic disease with up to 40% nonresponders and subsequent flares when TNF inhibitors are ceased." (PMID 20976214, 2010). "Although the use of TNF inhibitors has fundamentally changed the way rheumatoid arthritis (RA) is treated, not all patients respond well." (PMID 20593016, 2010). "The aims of this study were to do, comparative analysis of the levels of different cytokines such as LIF, TNF-alpha, IL-1, IL-6 and OSM, in the synovial fluid samples aspirated from 10 Rheumatoid arthritis (RA), 25 Osteoarthritis (OA) and 7 Mixed arthropathies (MA) patients." (PMID 21593968, 2008). "The incidence of malignancy may be higher in elderly patients, particularly those with rheumatoid arthritis (RA) or myelodysplastic syndrome, as well as in individuals receiving prolonged therapy with tofacitinib or ruxolitinib (oral JAK inhibitors) or anti-TNF agents." (PMID 40004842, 2025). "In the context of autoimmune diseases, such as systemic lupus erythematosus (SLE) and rheumatoid arthritis (RA), the crosstalk between IFN-I and TNFα is hypothesized to be of crucial importance, as literature suggests an inhibitory effect of TNFα on IFN-Is, and vice versa." (PMID 38596672, 2024). "Increased transcripts of IFI27 within VA and slightly less in noVA tissues, also reported in rheumatoid arthritis (RA), psoriasis, and UC, were especially observed in NV+ tissue samples and probably reflect a mixed response of IFN type I/III in an IFN-γ/TNF-α-enriched environment." (PMID 36282455, 2023). "We assessed 115 patients with active IA (64 rheumatoid arthritis (RA), 31 psoriatic arthritis and 20 ankylosing spondylitis) before and after using methotrexate (MTX) alone or tumor necrosis factor inhibitor (TNFi) with or without MTX co-medication (TNFi±MTX)." (PMID 36763689, 2023). "Tumor necrosis factor-α (TNF-α), interleukin-17 (IL-17), interleukin-6 (IL-6), interleukin-4 (IL-4) antibodies and other drugs have been proven useful in treating rheumatoid arthritis (RA), psoriasis, cytokine release syndrome (CRS), atopic dermatitis (AD) and other autoimmune diseases." (PMID 35844550, 2022). "TNFα, IL-1β, and hypoxia also up-regulate the expression of cytokines, including IL-6, CXCL8 (namely, IL-8), CCL2, CXCL11, CXCL12, and VEGF, as well as the expression of cytokine receptors such as TNFRSF9 in synovial fibroblasts derived from rheumatoid arthritis (RA) patients." (PMID 35967331, 2022). "TTP was also strongly expressed in the inflamed synovium of rheumatoid arthritis, which prompted the investigators to wonder why TTP failed to downregulate TNF expression and other inflammatory markers." (PMID 34207463, 2021). "We examined 115 patients with AA (64 rheumatoid arthritis (RA), 31 psoriatic arthritis and 20 ankylosis spondylitis) starting with methotrexate (MTX) monotherapy or tumor necrosis factor inhibitors (TNFi) with or without MTX co-medication." (PMID 34170978, 2021).
rheumatoid arthritis (continued). "Furthermore, it has been reported that TNF-α upregulates osteoclastogenic cytokine IL-34 production through the activation of NF-κB and JNK signaling in the synovial cells of rheumatoid arthritis (RA) patients." (PMID 33947456, 2021). "So far, there is no study that directly correlates TNF-α and SFRP-1 with CTX and P1NP, so that this study is expected to provide a better understanding of bone metabolism in patients with rheumatoid arthritis." (PMID 32190056, 2020). "In rheumatoid arthritis (RA), a disease characterized by high levels of pro-inflammatory cytokines, NFAT5 is translocated to the nucleus and highly expressed in fibroblast-like synoviocytes (FLS) after exposure to pro-inflammatory cytokines, including TNF-α and IL-1β." (PMID 33114289, 2020). "In patients with rheumatoid arthritis, soluble MICA failed to downregulate NKG2D on CD4+ T cells and CD8+ T cells, possibly due to counteractions of IL-15 and TNF-α." (PMID 30150983, 2018). "Rituximab (MabThera, Rituxan) is a chimeric, monoclonal anti-CD20 antibody approved for the treatment of rheumatoid arthritis (RA) in combination with methotrexate in patients with active RA who have not responded to at least one tumor necrosis factor (TNF) inhibitor." (PMID 26883119, 2016). "A selective anti-TNF-α effect is desirable for developing new antirheumatic drugs, since the administration of CCL2 monoclonal antibody to patients with rheumatoid arthritis did not ameliorate the disease and even aggravated the symptoms at higher doses." (PMID 25878716, 2015). "In a group of patients with acute rheumatoid arthritis, stable on MTX but with no adequate response to TNF inhibitors, Tabalumab showed indications of efficacy." (PMID 26270565, 2015). "Similar to stromal cells of the oral mucosa, no basal expression of NOD2 is detectable in Rheumatoid Arthritis Synovial Fibroblasts (RASFs), with NOD2 mRNA expression in these stromal populations only detectable after stimulation with POLYI:C, LPS, or TNFα." (PMID 24137162, 2013). "For instance, Tregs derived from patients with rheumatoid arthritis (RA) are defective in their ability to suppress cytokine production and to convey a suppressive phenotype to CD4+ effector T cells, which was at least partly restored upon treatment of TNFα neutralizing therapies." (PMID 19543397, 2009). "Notably, by the 48th hour, the serum TNF‐α and IL‐6 levels in the ACS group without rheumatoid arthritis had decreased to levels comparable to those of the controls." (PMID 39669190, 2024). "Moreover, a recent study demonstrated that similar to osteoarthritis (OA) and rheumatoid arthritis (RA), patients with hemophilic arthropathy (HA) exhibit increased levels of progranulin (PGRN), a molecule known for its protective role against the catabolic effects of TNFα." (PMID 39337384, 2024). "Anti-TNF therapies can increase total cholesterol, high-density lipoprotein (HDL), low-density lipoprotein (LDL), triglycerides, and Apo B levels in patients with PsA and rheumatoid arthritis (RA) without changing the atherogenic index." (PMID 34631754, 2021). "Moreover, synoviocytes from patients with rheumatoid arthritis constitutively express high levels of PTX3 mRNA and protein in vitro, and these were not affected by neutralization of TNF-α or IL-1β." (PMID 31787987, 2019). "Unlike the known thyroidal side effects of immunomodulatory agents used in hepatitis C and cancer treatment, the immunomodulatory agents (anti-TNF-α and RIX) used in treatment of rheumatoid arthritis did not lead to significant changes in thyroid function nor autoimmunity." (PMID 28824542, 2017). "Rheumatoid arthritis patients with or without IR were not statistically different in relation to disease duration and serum RF and anti-CCP levels and frequency in prednisone and antimalarials and methotrexate and leflunomide use and anti-TNF-α therapy." (PMID 27340510, 2016).
rheumatoid arthritis (continued). "On the other hand, age, gender, alcohol consumption, coronary heart disease, rheumatoid arthritis, the use of oral corticosteroids or NSAIDs, body mass index, and the serum proinflammatory markers resistin, hs-CRP, TNF-α, and IL-6 were not significantly related to logLSburden." (PMID 23902899, 2013). "Non-selective pharmacological inhibition of TNF using etanercept (ETN; a fusion protein consisting of TNFR2 attached to Fc of IgG that target both forms of TNF) has been effective in treating inflammatory diseases such as rheumatoid arthritis and inflammatory bowel disease." (PMID 36186984, 2022). "However, when TNF-α signaling is not tightly controlled, dysregulation of peripheral TNF-α signaling can contribute to the development of inflammatory and autoimmune disorders including septic shock and rheumatoid arthritis." (PMID 30804748, 2019). "Furthermore, the plasma levels of NT-proBNP, CRP, and TNF-α in patients with rheumatoid arthritis (RA) without clinical heart failure are higher than in control groups, suggesting that increases in the NT-proBNP levels in RA patients are related to inflammation." (PMID 28570595, 2017). "Although several trials using anti-TNF-α blockers in patients with COPD have revealed no benefits, a large observational study reports reduced hospitalization rates in patients diagnosed with both COPD and rheumatoid arthritis (RA) and receiving TNF-α inhibitors." (PMID 26523550, 2015).
Insulin resistance (3,892 papers, 2003 to 2026). Increased resistance towards insulin, that is, diminished effectiveness of insulin in reducing blood glucose levels. "Among inflammatory mediators implicated in GDM, tumor necrosis factor-α (TNF-α) is a key driver of insulin resistance." (PMID 41596503, 2026). "The results suggest that while TNF-α is primarily associated with abdominal obesity, IL-6 is a strong predictor of lipid disorders and insulin resistance, indicating different mechanisms by which these cytokines influence metabolic disturbances." (PMID 40137151, 2025). "Sweet potato anthocyanins have decreased levels of pro‐inflammatory cytokines such as TNF‐α, which are usually elevated in individuals with diabetes and eventually cause insulin resistance." (PMID 40918166, 2025). "While TNF-α plays an important role in the defense against pathogens51high circulating levels in blood have been associated with the development of insulin resistance, diabetes and cardiovascular disease." (PMID 40665094, 2025). "In response, the body releases pro-inflammatory cytokines, notably interleukin-6 (IL-6) and tumor necrosis factor-alpha (TNF-α), which have been closely linked to insulin resistance and beta-cell dysfunction." (PMID 40742490, 2025). "In GDM, TNF-α is considered an independent risk factor for dysglycemia due to this ability to disrupt insulin action, leading to increased insulin resistance." (PMID 40722699, 2025). "TNF and IL-6 are central inflammatory cytokines implicated in lipid metabolism disorders and insulin resistance." (PMID 41304686, 2025). "Some fundamental studies have indicated that insulin resistance is closely associated with an increase in the release of inflammatory factors, such as TNF-α and IL-6." (PMID 40936909, 2025). "Proinflammatory and senescence-associated secretory phenotype (SASP) cytokines, such as TNF, are known to inhibit myogenesis and induce insulin resistance in skeletal muscle." (PMID 40502786, 2025). "Elevated levels of pro-inflammatory cytokines such as interleukin-6 (IL-6), C-reactive protein (CRP), and tumor necrosis factor-α (TNF-α) are associated with insulin resistance by interfering with insulin receptor signaling." (PMID 40137149, 2025). "TNF-α, while essential in early gestation, is also implicated in insulin resistance and metabolic dysregulation in GDM." (PMID 41303355, 2025). "Factors associated with adipose tissue, including tumor necrosis factor alpha (TNF-α), interleukin-6 (IL-6), and IL-1b, are linked to systemic insulin resistance." (PMID 39941760, 2025). "Integrative analysis highlighted lipid-related mechanisms (cellular lipid response, PI3K-AKT signaling, insulin resistance, and non-alcoholic fatty liver disease) and inflammation-associated pathways (TNF/IL-17 signaling)." (PMID 40699849, 2025). "Dysbiosis can also increase inflammatory cytokines like TNF-α and IL-6, which are linked to insulin resistance and metabolic dysfunction." (PMID 40926269, 2025). "MASLD is characterized by chronic low-grade inflammation, which is characterized by increased levels of TNF-α and IL-6, which are in turn associated with insulin resistance and T2DM onset." (PMID 41220583, 2025). "Inflammatory factors produced by macrophages (TNF-α, IL-6, and IL-1β) have been shown to affect lipolysis and cause insulin resistance." (PMID 40764506, 2025). "In patients with T2DM, it is often accompanied by elevated pro-inflammatory factors (e.g., TNF-α, IL-6, IL-1β), which are not only closely associated with the development of insulin resistance, but also promote pancreatic β-cell dysfunction." (PMID 40351422, 2025). "Elevated levels of IL-6 and TNF-α are associated with chronic low-grade inflammation, contributing to insulin resistance, impaired glucose metabolism and increased cardiometabolic risk." (PMID 40362742, 2025).